TFEB (transcription factor EB)
Diseases named in the same sentence as TFEB in open-access papers (continued):
Sharing a sentence is not in itself a finding about the gene and the disease.
atherosclerosis (continued). "Given the consummated investigations and the unmet challenges, this article focuses on the current cognizance of the several ways to activate TFEB and the integrated network mechanism of TFEB linking lipid homeostasis with atherosclerosis." (PMID 33679452, 2021). "For example, initial observations by scientists investigating LSDs enabled researchers to study the key role of the transcription factor TFEB, the master regulator of lysosome biogenesis, in the development of atherosclerosis." (PMID 33855029, 2021). "Nuclear transcription factor EB (TFEB) prevents atherosclerosis by activating macrophage autophagy and promoting lysosomal biogenesis." (PMID 33462182, 2021). "Over the past years, with the study of lipid homeostasis in atherosclerosis showing the situation of the explosive growth, the regulatory role of TFEB has also been gradually explored." (PMID 33679452, 2021). "In-depth research is warranted to develop potent agents against TFEB to alleviate or reverse the progression of atherosclerosis." (PMID 33679452, 2021). "In vitro studies have demonstrated that increasing lysosomal biogenesis through TFEB overexpression can rescue the lipid-induced lysosomal dysfunction, reduce inflammasome activation and decrease atherosclerosis progression." (PMID 33855029, 2021). "Many studies have confirmed that TFEB inhibits the progression of atherosclerosis mainly by promoting lipid degradation." (PMID 33679452, 2021). "During atherosclerosis progression, lipid overload in macrophages for prolonged periods leads to TFEB desensitization." (PMID 33973365, 2021). "The regulation mechanism of TFEB in immune inflammation has been roughly determined, but the regulation of lipid homeostasis of TFEB in atherosclerosis needs to be fully studied." (PMID 33679452, 2021). "Recent evidence suggests that activation of TFEB alleviates atherosclerosis development in mice by promoting lysosomal biogenesis and autophagy induction." (PMID 33203874, 2020). "In atherosclerosis, Tre induced macrophage autophagy-lysosomal biogenesis and produced similar effects to TFEB overexpression in macrophages." (PMID 31947943, 2020). "Further, endothelial specific overexpression of TFEB suppresses endothelial inflammation and attenuate atherosclerosis in mice." (PMID 31515484, 2019). "In particular, activation of TFEB by trehalose ameliorates atherosclerosis development in mice by promoting lysosome regeneration, autophagy induction, and inhibition of inflammasome activity in macrophages." (PMID 31515484, 2019). "Endothelial specific overexpression of TFEB suppresses endothelial inflammation and attenuate atherosclerosis in mice." (PMID 31515484, 2019). "Transcription factor EB (TFEB) prevents atherosclerosis by activating macrophage autophagy to promote lipid degradation." (PMID 28005078, 2016). "Thus, TFEB is considered a protective factor against the occurrence and development of atherosclerosis." (PMID 41516224, 2025). "Answers to these questions may help identify TFEB SUMOylation sites as new therapeutic targets for atherosclerosis treatment." (PMID 41516224, 2025). "TFEB overexpression in these cells restores lysosomal function, promotes autophagy, and reduces inflammation, highlighting its therapeutic potential in vascular inflammation and atherosclerosis." (PMID 40426881, 2025). "Furthermore, activation of TFEB using the disaccharide trehalose reduced atherosclerosis progression, highlighting the therapeutic potential of autophagy activation for atherosclerosis treatment." (PMID 38433753, 2024). "Overexpression of a transcription factor EB (TFEB) that drives autophagy-lysosomal biogenesis in macrophages can reduce arteries atherosclerosis, help reduce lipid-mediated lysosomal dysfunction, increase cholesterol efflux and inactivate inflammasome activation." (PMID 36683743, 2023).
atherosclerosis (continued). "These lines of evidence have emphasized the benefits of TFEB for vascular diseases; however, whether TFEB is involved in the bromelain-mediated protection from hepatic lipid accumulation and atherosclerosis requires further investigation." (PMID 36670934, 2022). "Notably, TFEB makes a possible therapeutic target of atherosclerosis by regulating lipid metabolism." (PMID 33679452, 2021). "The functional regulation of SIRT1 and TFEB by berberine could be exploited as a potential therapeutic strategy for atherosclerosis." (PMID 33639613, 2021). "For the reason that lipid metabolism is closely related to atherosclerosis, it is hypothesized that TFEB also regulates lipid metabolism in atherosclerosis." (PMID 33679452, 2021). "Additionally, a recent publication demonstrated that SR class B type I (SR-BI) is necessary to maintain macrophage autophagy in atherosclerosis through a mechanism involving TFEB expression and VPS34/Beclin-1 recruitment." (PMID 33855029, 2021). "In addition, we delineate some TFEB activators as potential therapeutic candidates in mitigating the pathological progression of atherosclerosis." (PMID 33679452, 2021). "Therefore, the transcription function of TFEB has attracted the attention of scientific researchers in the atherosclerosis field." (PMID 33679452, 2021). "TFEB has been shown to play a protective role in endothelial cells via migrating oxidative stress and upregulating the expression of multiple antioxidant genes, thereby slowing down the progression of atherosclerosis." (PMID 34490237, 2021). "Despite the considerable amount of work being conducted to understand the role of TFEB in cell metabolism and lipid homeostasis, several instances of its involvement in the regulation of lipid levels in atherosclerosis and related diseases have only recently been identified." (PMID 33679452, 2021). "Although TFEB activation by genetic or pharmacological methods can alleviate atherosclerosis, the molecular basis for regulation of TFEB activation is unknown." (PMID 33973365, 2021). "Then, we analyze the current knowledge of TFEB in the vascular system, placing particular emphasis on its regulatory role in angiogenesis and on the involvement of the vascular unit in inflammation and atherosclerosis." (PMID 33912071, 2021). "Modulation of the SCD1/TFEB‐mediated lipophagy machinery may offer novel therapeutic approaches for the treatment of atherosclerosis." (PMID 31119852, 2019). "Moreover, trehalose was shown to exhibit protective effects on atherosclerosis, which is attributed to enhanced TFEB-dependent autophagy signaling in macrophages." (PMID 31515484, 2019). "More recently, TFEB overexpression was shown to reverse the gradual decline in the autophagy–lysosome system that occurs in lipid loaded cells with dysfunctional lysosomes, abolishing apoptosis and reducing IL-1β production, and consequently atherosclerosis." (PMID 29997514, 2018). "Thus, lysosomal biogenesis in macrophages stimulated by TFEB may serve as a protective factor for atherosclerosis." (PMID 37239823, 2023). "Therefore, AMPK/TFEB signaling may be crucial in bromelain-mediated anti-hyperlipidemia, antioxidant, and anti-inflammatory effects, effecting the amelioration of atherosclerosis." (PMID 36670934, 2022). "This suggests that TFEB activation to stimulate autophagy- and antioxidant-related proteins is the mechanism by which bromelain provides protection from the deregulation of lipid metabolism, oxidative stress, and inflammation, leading to the mitigation of atherosclerosis." (PMID 36670934, 2022). "Consistent with our hypothesis, studies in atherosclerosis and liver fibrosis have indicated that increased TFEB expression abrogates macrophage apoptosis and decreases proinflammatory cytokine levels, which reduces atherosclerosis plaque formation or fibrogenesis." (PMID 31947943, 2020).
atherosclerosis (continued). "In summary, our findings give fresh and exciting insight into the communication between oxLDL‐induced VSMC foam cell formation and lipophagy signalling, which could contribute to the development of drugs for atherosclerosis that target the SCD1/TFEB signalling pathway." (PMID 31119852, 2019). "Thus, HY-SDT may be beneficial for atherosclerosis via TFEB regulation to ameliorate lipid overload in atherosclerotic plaques." (PMID 28005078, 2016). "Extending these insights, our recent work showed that Dax1 promotes atherosclerosis by interacting with LXR and the transcription factor EB (TFEB) to inhibit cholesterol transport and autophagy." (PMID 41438090, 2025). "The activation of lysosome biogenesis by TFEB overexpression suppresses cholesterol crystal-induced NLRP3 inflammasome, attenuating the progression of atherosclerosis, in vitro and in vivo." (PMID 29997514, 2018). "Laminar shear stress, known to protect against atherosclerosis but not oscillatory shear stress, induces TFEB activation." (PMID 33912071, 2021). "We studied the effects of berberine-induced TFEB activation via SIRT1 on autophagy and apoptosis in peritoneal macrophages and whether it protected against atherosclerosis." (PMID 33639613, 2021). "While Stearyl coenzyme A desaturase 1 (SCD1) can promote TFEB-mediated lipophagy to interfere with foam cell formation and modulation of the SCD1/TFEB machinery may offer novel therapeutic approaches for atherosclerosis." (PMID 34490237, 2021). "The absence of ATG5 or p62 abrogates TFEB's ability to reduce atherosclerosis, plaque complexity, macrophage apoptosis and aggrephagy of p62-enriched protein aggregates." (PMID 28589926, 2017). "Our findings with dual mφTFEB-TG/ATG5-KO macrophages were mirrored with dual mφTFEB-TG/p62-KO mice where again TFEB's protective effects on atherosclerosis and lesion complexity were abrogated in the absence of p62." (PMID 28589926, 2017). "Consistent with TFEB's dependence on autophagy, the dual mφTFEB-TG/ATG5-KO mice were no longer protected from atherosclerosis with similar serum cholesterol and other common serum metabolites to controls." (PMID 28589926, 2017).
melanoma (32 papers, 2016 to 2025). A malignant, usually aggressive tumor composed of atypical, neoplastic melanocytes. "Previous work revealed that depletion of TFEB in melanoma cells caused reduced proliferation and lower glucose and glutamine uptake and, consequently, reduced glycolysis, glutaminolysis, and slower tumor growth in vivo." (PMID 41275493, 2025). "In this study, we demonstrated that TFEB exerts a relevant impact on the behaviour of BRAF-mutated melanomas." (PMID 37160873, 2023). "Of note, genes downregulated by TFEB knockdown are significantly associated with the gene set regulated by MITF in melanoma cells." (PMID 36372230, 2022). "Consistent with this study, downregulation of TFEB increased colorectal cancer risk and promoted melanoma metastasis." (PMID 33803301, 2021). "The effects of blocking mTOR activity on the subcellular location of TFEB have the potential to modulate the autophagy response, which has been linked to increased vesicle trafficking and chemoresistance in melanoma." (PMID 32881934, 2020). "While our observations do not exclude other reported mechanisms in BRAFi-associated autophagy in melanoma, TFEB/ZKSCAN3 constitutes direct mediators of the autophagy–lysosomal program that affects the responsiveness of melanoma to oncogenic stress." (PMID 30979895, 2019). "Thus, TFEB is primarily responsible for BRAFi-associated transcriptional activation of autophagy and lysosomal function in melanomas." (PMID 30979895, 2019). "The presence of low levels of β-Catenin, associated with low MITF levels in V600BRAF melanoma cell lines, could be linked to autophagy activation in these cell lines, as proved by the high TFEB levels revealed in this study." (PMID 30634982, 2019). "Together with microphthalmia-associated transcription factor, transcription factor E3 and transcription factor EC, TFEB belongs to the microphthalmia family of bHLH-leucine zipper transcription factors that may be implicated in human melanomas, renal and pancreatic cancers." (PMID 33252196, 2020). "Here, we reveal the functional specialization of MITF, TFE3, and TFEB and their impact on melanoma progression." (PMID 41275493, 2025). "Meanwhile, in MITF-low invasive melanoma, transcription factor EB (TFEB) and TFE3 drive lysosomal biogenesis and function to support tumor growth and invasiveness through nutrient recycling and metabolic adaptation." (PMID 41155412, 2025). "In melanoma, TFEB has also been reported to be able to affect cell metabolism and proliferation by regulating the DUSP‐1/ERK1/2 pathway." (PMID 38938061, 2024). "We therefore investigated its localization by subcellular fractionation and observed that in WM1716 melanoma cell line, TFEB was present in both nucleus and cytoplasm." (PMID 38750105, 2024). "Taken together, our results revealed the association of lysosome function to melanoma metastasis via the GNPTAB, IGF2R, and TFEB axis." (PMID 38750105, 2024). "In melanoma, TFEB silencing markedly impaired cell cycle: this phenotype was mirrored by shTFEB NSCLC tumors that had also a decreased intratumor proliferation." (PMID 39107857, 2024). "Further, our observations suggested that perturbing hydrolase transport in melanoma stimulates lysosome biogenesis as a consequence of TFEB expression upregulation." (PMID 38750105, 2024). "In TFEB-silenced melanoma cells, cholesterol synthesis is impaired, and the uptake of glucose and glutamine is inhibited, leading to a reduction in glycolysis, glutaminolysis and oxidative phosphorylation." (PMID 37160873, 2023). "For the first time, the present study demonstrates complex molecular signalling orchestrated by TFEB in the control of proliferation and metabolism in melanoma cells." (PMID 37160873, 2023). "In melanoma cells, TFEB silencing correlates with ERK1/2 dephosphorylation at the activation-related p-Thr185 and p-Tyr187 residues." (PMID 37160873, 2023).
melanoma (continued). "When TFEB is downregulated, melanoma cells respond by decreasing the uptake of glucose and glutamine; glycolytic and TCA anaplerotic flux; OXPHOS; and the synthesis of lactate, ATP and cholesterol." (PMID 37160873, 2023). "Treating 501Mel cells with the mTOR pan-inhibitor Torin-1 (1 μM, 3 hours) resulted in increased nuclear localization of the endogenous TFEB protein, suggesting that mTOR activity contributes to the cytoplasmic retention of TFEB in melanoma cells." (PMID 32881934, 2020). "We have shown that both MITF and TFEB negatively affect the expression of endogenous MITF in both melanoma cell lines used in this study and would therefore expect their increased nuclear presence upon Torin-1 treatment to further repress MITF expression." (PMID 32881934, 2020). "Collectively, these data indicate that MITF and TFEB are able to regulate each other’s mRNA and protein expression in human 501Mel and Skmel28 melanoma cells." (PMID 32881934, 2020). "On the other hand, suppression of Yin Yang 1 (YY1), which is a cofactor of TFEB and contributes to the regulation of genes related to autophagy and lysosome biogenesis, evoked enhanced anti-melanoma efficiency of vemurafenib both in vitro and in vivo." (PMID 32340261, 2020). "Taken together, these data indicate that the mTOR signaling pathway is active in melanoma cells and can affect import of TFEB into the nucleus." (PMID 32881934, 2020). "Consistently, we observed a correlation between TFEB S142 phosphorylation and autophagy–lysosomal suppression in vitro and in vivo, underscoring a key role of autophagy–lysosomal output of TFEB in melanoma." (PMID 30979895, 2019). "Here, the authors describe that BRAF inhibition induces the autophagy-lysosomal function in BRAF-mutant melanomas via modulation of the TFEB and ZKSCAN3 transcriptome, which downregulates TGF-β and suppresses melanoma progression." (PMID 30979895, 2019). "Further, ZKSCAN3 depletion synergized with TFEB overexpression and resulted in growth inhibition of A375 xenograft melanoma." (PMID 30979895, 2019). "To understand the role of ERK in TFEB regulation in BRAFV600E melanoma, we performed co-immunoprecipitation (co-IP) and found that more TFEB co-IP with ERK in A375 than in MeWo cells, and that this association was disrupted by PLX4720 in A375 cells." (PMID 30979895, 2019). "MITF thus has a regulatory role within lysosomal function and autophagy in melanoma tumors, distinct from the related TFEB and TFE3 factors." (PMID 30705290, 2019). "Here, we identify the molecular basis by which BRAFV600E controls the transcriptional machinery of the autophagy–lysosomal pathway through TFEB in melanoma." (PMID 30979895, 2019). "We next evaluated the effects of TFEB S142 phosphorylation on the metastasis of BRAFV600E melanoma in an immunocompetent background using the B16-F10 (BRAFWT) syngeneic model." (PMID 30979895, 2019). "To uncover the signaling pathways altered by TFEB phosphorylation, we performed unbiased RNA-seq of A375 melanoma xenografts." (PMID 30979895, 2019). "As BRAFV600E inactivates TFEB in melanoma, it is plausible that endogenous TFEB S142 phosphorylation by the BRAFV600E–ERK axis in melanoma similarly contributes to tumor progression." (PMID 30979895, 2019). "Notably, immunohistochemistry using tissue sections from three different human melanomas (melanomas 1–3) revealed a significant proportion of melanoma cells exhibiting nuclear staining of TFEB, suggesting that, in vivo, mTORC1 signaling is suppressed." (PMID 41275493, 2025). "Since in melanoma TFEB silencing reduces the phosphorylation and activity of ERK1/2, which in turns phosphorylates and activates the cleavage of SREBP2, the main transcription factor of cholesterol homeostasis genes, we first investigated if these events occur also in NSCLC cells." (PMID 39107857, 2024).